BCL2L1 (BCL2 like 1)
Diseases named in the same sentence as BCL2L1 in open-access papers (continued):
Sharing a sentence is not in itself a finding about the gene and the disease.
cancer (continued). "A model has been proposed that SF3B-targeting splicing modulators preferentially perturb RNA splicing of MCL1 and BCL2A1, but not of BCL2L1 (BCLxL), leading to selective cytotoxicity in MCL1- or BCL2A1-dependent cancer cells." (PMID 37562845, 2023). "BCL2L1 methylation is a predictor of MCL1 inhibitor response in CNS and non-CNS pediatric cancers." (PMID 39846250, 2025). "While MCL1, BCL2L1, or BCL2L2 were ubiquitously expressed, BCL2 and BCL2A1 demonstrated tissue/lineage-selective expression with very low/no expression across most of the cancer cell lines and TCGA tumor tissues." (PMID 30635584, 2019). "However, cancer cells relying on BCL2 and lacking MCL1/BCL2L1 might also be more resistant to CGs." (PMID 37904054, 2024).
tumor (1,142 papers, 2001 to 2026). "Given that BCL2L1 (promoting cell survival) is closely linked to promoting tumor progression, we explored its underlying mechanisms related to CLU." (PMID 40606578, 2025). "We find that BCL2L1, which encodes the anti-apoptotic protein BCL-XL, is highly expressed predominantly in tumor cells, where it likely plays a crucial role in tumor cell survival as drug tolerance and acquired resistance to EGFR-TKIs emerge." (PMID 39122703, 2024). "We found that high BCL2L1 expression in the primary tumor was associated with metastasis at diagnosis and a worse EFS." (PMID 36982681, 2023). "Amplification of MCL1 and BCL2L1 (encodes BCL-XL) were found to be among the most frequent chromosomal gains in a study of over 3000 samples representing 26 tumour types." (PMID 29769323, 2018). "As a member of the antiapoptotic Bcl-2 family, BCL2L1 is hypomethylated and highly expressed in chemotherapy drug (e.g. cisplatin and paclitaxel) -resistant tumor cells in vitro and has been proven to be associated with drug resistance and recurrence of solid tumor cancer." (PMID 37889117, 2023). "Therefore, prior to the transfer into tumor-bearing mice, lin28Tg CTLs were transduced with bcl2l1, the gene that encodes the pro-survival factor Bcl-xL." (PMID 37696797, 2023). "The contribution of elevated BCL2L1 expression to driving resistance to MCL loss was further confirmed in a large genetic knock-down screen of a cell panel comprising 100s of cell lines from different tumor types." (PMID 32645016, 2020). "NFKB is activated TRADD-, TRAF3- and FADD-dependently and also plays a key role in the survival of tumor cells by inducing expression of anti-apoptotic genes such as Bcl2, Bcl2l1, vascular endothelial growth factor (VEGF), and X-linked inhibitor of apoptosis (XIAP)." (PMID 19077262, 2008). "In vivo, xenograft experiments demonstrated that PBX1 overexpression suppressed tumor growth, which was further augmented by BCL2L1 knockdown." (PMID 42086530, 2026). "The volcano plot showed high expression of tumor markers such as SLC2A1 and BCL2L1 in E4, suggesting a strong proliferative advantage and anti-apoptotic ability in tumor progression." (PMID 40463392, 2025). "On the other hand, it also displayed alterations in the expression of key genes, including SOX9, E2F family, KRAS, BCL2L1, and MYC, indicative of a predisposition for BC tumor initiation, stemness, and progression." (PMID 40801146, 2025). "We next determined the mRNA levels of classical markers of apoptosis, two splicing variants of bcl2l1 (Bcl-xL, anti-apoptotic and oncogenic marker; and Bcl-xS, pro-apoptotic tumor suppressor)." (PMID 38990489, 2025). "We extended these data across multiple pediatric tumor types, showing that BCL2L1 methylation is a broad predictor of MCL1 dependency in vitro and in vivo." (PMID 39846250, 2025). "Histological and immunohistochemical analyses confirmed the role of CLU in tumor formation through BCL2L1 upregulation." (PMID 40606578, 2025). "Comparison of pHGG with nonmalignant tissue specimens showed cg00300298 hypermethylation, verifying that BCL2L1 was hypermethylated in both pHGG cell lines (P = 0.005) and tumor samples (P < 0.0001)." (PMID 39846250, 2025). "For example, the BCL2L1 gene plays a crucial role in cell survival following radiation exposure, and the inhibition of BCL2L1 combined with radiotherapy significantly hinders tumor growth in vitro and in vivo." (PMID 39273235, 2024). "BCL2L1 expression was higher in the tumor than in the normal tissue in UCEC, COAD, and STAD patients, whereas it was higher in the normal tissue than in the tumor tissue in LUSC." (PMID 38542508, 2024).
tumor (continued). "Our study showing that BCL2L1 expression is higher in tumor cells than in non-tumor cells supports the outcome of this clinical trial." (PMID 39122703, 2024). "The results show that BAX and BCL2L1 were significantly (p < 0.001) higher in the tumor tissue than in the normal tissue when comparisons were made, whereas NFKBIA was significantly (p < 0.001) higher in the normal than in the cancer tissue." (PMID 38542508, 2024). "We demonstrated that BCL2L1 is specifically expressed in tumor cells and plays an important role in tumor survival, especially in DTPs and in cells that have acquired resistance to osimertinib treatment." (PMID 39122703, 2024). "Comparing the four canonical MB subgroups in detail, Group 3 tumours both expressed BCL2L1 (BCL-XL) and BBC3 at significantly higher levels than the other subgroups and showed significantly lower BCL2L12 expression than the MBSHH and MBWNT subgroups." (PMID 38942989, 2024). "Real-time PCR analysis revealed an increased Bcl2l1 gene expression in BMNs incubated with tumor cell supernatant, which was confirmed at the protein level by western blot." (PMID 38177532, 2024). "Overall, our findings indicate that BCL2L1/BCL-XL expression is important for tumor cell survival as EGFR-TKI resistance emerges." (PMID 39122703, 2024). "Several studies have shown that MCL1 and BCL2L1 (BCLXL) are frequently overexpressed in various tumor types." (PMID 39200265, 2024). "Although we observed intra-tumor heterogeneity, Bcl2l1 expression in tumor lesions was higher than in non-tumor lesions in all states, whereas Mcl1 expression was less tumor-specific and relatively lower in recurrent lesions." (PMID 39122703, 2024). "Taken together, Bcl2l1 is more highly expressed in residual tumor cells in comparison to neighboring stromal and immune cells." (PMID 39122703, 2024). "Our findings suggest that tumor-specific BCL2L1 expression likely plays an important role in tumor cell survival, especially in DTP and recurrent states." (PMID 39122703, 2024). "In all cases, a high percentage of tumor cells expressed BCL2L1 and MCL1 as anti-apoptotic genes of the BCL-2 family." (PMID 39122703, 2024). "In PCa, the STAT protein family promotes tumor progression and mediates therapy resistance by regulating oncogene and pro-survival gene transcription (e.g., BCL2L1, MCL1, MYC, CCND1)." (PMID 35207527, 2022). "Using single cell sequencing, we identified the CNV of chromosome 20q in LN metastasis compared to the primary tumor and found that amplification of AURKA (protein: Aurora Kinase A (Aurora A)) and BCL2L1 (protein: Bcl-xL) was associated with LN metastasis." (PMID 36077449, 2022). "miR-185-5p targets ROCK2, ELK1, ELK3, IGF2, RAGE, BCL2, BCL2L1, and many other genes to suppress tumor cell migration and invasion." (PMID 35223832, 2022). "The area under the curve (AUC) of BCL2L1 was 0.982, indicating that BCL2L1 can be an ideal biomarker to distinguish OC from non-tumor tissues." (PMID 35401186, 2022). "The analysis revealed that BCL2L1 (BCL-xL) and MCL-1 were exclusively expressed in tumour regions marked by the hallmark chromosomal alterations, namely gain in chromosome 7 and loss of chromosome 10." (PMID 35473984, 2022). "In the following exploration, we have focused on the roles of SPTBN2 and BCL2L1 in the tumor microenvironment from the perspective of immune modulation by retrieving data from the TIMER database." (PMID 34179092, 2021). "Cases sequenced from metastatic sites showed a significantly elevated rate of BCL2L1 amplification compared with primary-site tumor samples (16% [17/107] vs. 2% [1/41], p = 0.0248), particularly in cases sequenced from liver metastases (20%; 7/35 cases)." (PMID 32892208, 2021). "Comparing tumor-infiltrating versus blood Treg cells, we identified some common shared signature genes of tumor-infiltrating Treg cells, including some genes whose protein products are targetable such as CD177 and BCL2L1 (encoding BCL-XL)." (PMID 34831009, 2021).
tumor (continued). "The results above delineate the alteration of SPTBN2 and BCL2L1 in view of tumor immune modulation mediated by CCL27 and CCR10, resulting in a reduced abundance of CD4+ T cells and dendritic cells." (PMID 34179092, 2021). "In particular, upon c-Src activation, STAT3 promotes tumor cell survival and proliferation by transactivating BCL2L1 (that encodes the Bcl-XL protein) and MCL1, two crucial anti-apoptotic genes that override cell death regulatory pathways." (PMID 31569642, 2019). "Apart from that, MCPIP1 is recognized as a tumor suppressor due to its induction of apoptosis of tumor cells, for instance by selectively enhancing mRNA decay of antiapoptotic gene transcripts, including Bcl2L1, Bcl2A1, RelB, Birc3, and Bcl3." (PMID 31651935, 2019). "In contrast, PTEN, the anti-tumor indicator, was upregulated after knockdown of BCL2L1 and downregulated in the recuse experiments." (PMID 31508368, 2019). "There is therefore interest in developing therapeutic tools that alter the balance of BCL2L1 splice isoforms in tumour cells to promote apoptosis." (PMID 29693622, 2018). "SSOs have been used to modify splicing of BCL2L1, disrupting tumour growth in vivo by targeting the 5′ splice site of exon 2 of BCL2L1 pre-mRNA." (PMID 29693622, 2018). "Forced expression of activated STAT3 in fibroblast cell lines resulted in 3-6 fold up-regulation of MYC, CCND1 (coding for cyclin D1) and BCL2L1 (BCL-XL) mRNA, and permitted tumor formation in nude mice." (PMID 29207662, 2017). "Following DEN/PB-exposure Bcl-3Hep mice showed a significantly reduced mRNA expression of anti-apoptotic factors including Xiap (p < 0.001), Bcl2l1 (p < 0.05) and Bcl2 (p < 0.05) in the liver in parallel to increased rates of apoptosis in tumor tissue." (PMID 28915576, 2017). "Taking BCL2L1 as an example, it can influence tumor cell apoptosis by regulating the opening of the outer mitochondrial membrane channel." (PMID 27477450, 2016). "To identify tumor subtypes that have significant frequency of BCL2L1 amplification, we performed data mining using The Cancer Genome Atlas (TCGA) database." (PMID 26134786, 2015). "In the subset of tumours suited for quantitative PCR analyses, we profiled the mRNA expression of RELA (encoding for RelA/p65) and a number of NF-κB target genes, such as BCL2L1 (Bcl-xL), CCND1 (Cyclin D1), CCND2 (Cyclin D2) and NFKBIA (IκBα)." (PMID 17622249, 2007). "In addition, CEBPG functioned as a key regulatory factor that increased tumor malignancy through BCL2L1-mediated survival pathways to some extent." (PMID 41958675, 2026). "CLU overexpression promoted tumor growth, which was significantly inhibited by BCL2L1 knockdown." (PMID 40606578, 2025). "However, BCL2L1 was highly expressed specifically in tumor cells, while MCL1 was expressed at lower levels in tumors compared to non-tumor cells." (PMID 39122703, 2024). "However, our analysis of ST data showed a positive correlation between tumor cell proportions and Bcl2l1 expression levels, indicating that DTP cells exhibit high Bcl2l1 expression regardless of co-localized non-tumor cells." (PMID 39122703, 2024). "In summary, our multifaceted approach, incorporating new technologies such as scRNA-seq and ST as well as conventional cell line systems and animal models, highlights the importance of BCL2L1 expression in tumor cell survival as drug resistance emerges and cells acquire resistance to EGFR-TKI." (PMID 39122703, 2024). "Also frequent is the amplification of chromosomal region 20q11.21, which harbors antiapoptotic genes like BCL-XL/BCL2L1, as well as duplications of oncogenes and deletions of tumor-suppressor genes." (PMID 38254390, 2024).
tumor (continued). "Because BCL2L1 plays an important role in tumor cell survival and proliferation, we next investigated whether overexpression of BCL2L1 could restore tumor growth in shHIGD2A.1-infected cells." (PMID 37041638, 2023). "As a consequence, PELI1 inhibited the noncanonical NF‐κB–induced expression of the anti‐apoptotic gene BCL2 like 1 (Bclxl; also known as BCL2L1), leading to an enhancement of the IR‐induced apoptosis signaling pathway and ultimately promoting IR‐induced apoptosis in tumor cells." (PMID 34738714, 2022). "Furthermore, we used the subject operating characteristic (ROC) curve to analyze the effectiveness of BCL2L1 expression levels in distinguishing OC tissues from non-tumor tissues." (PMID 35401186, 2022). "A study observed that anti-PD-1 therapy induces hyper-progression with clonal expansion of tumor-infiltrating Treg cells with upregulation of some genes, including CD177 and BCL2L1 in a leukemic patient, the two genes we found to be elevated specifically in tumor-infiltrating Treg cells." (PMID 34831009, 2021). "In 786-O primary tumor cell line we observed decrease expression of genes of insulin-associated proteins (IRS2, CBL), transcription regulators (AEBP1), PI3 kinase signaling (AKT1, BCL2L1) as well as lipid metabolism genes (ACOX1)." (PMID 30929166, 2019). "BCL2L expression in head and neck patients has shown to be associated with a favorable outcome in a study involving 400 patients while another study associates BCL2L1 expression with tumor recurrence." (PMID 28443095, 2017). "BCL2L1 protein expression was localized in the cytoplasm of the tumor cells." (PMID 26048755, 2015). "High expression level of apoptosis related genes, such as BCL2L1, might act as a trigger that determines tumor morphogenesis and be one of the genes responsible for horizontal growth, resulting in the laterally spreading morphology of LSTs." (PMID 26048755, 2015). "Furthermore, transcription factor analysis suggested that CEBPG might regulate BCL2L1 expression to promote tumor survival and migration." (PMID 41958675, 2026). "It was found that the organoid cultured in vitro could largely maintain the DNA methylation patterns of gene promoter regions as those of in vivo tumor tissues, including the genes BCL2L1, IMPDH2, and TGFBI, which have been reported to be associated with CRC progression." (PMID 37345888, 2024). "Similarly, BCL2L1 expression was significantly (p < 0.001) higher in the tumor than in the normal tissue in UCEC, COAD, and STAD patients, whereas CASP8 was significantly (p < 0.001) higher in the normal tissue than in the tumor tissue (either p < 0.05 or p < 0.001) in LUSC." (PMID 38542508, 2024). "After the critical stage (stage IIB), signaling receptor genes (IL4R) were highly expressed, which might have triggered the phosphorylation of PI3K and AKT proteins and further upregulated the expression of the apoptosis inhibitor BCL2L1 and enhanced tumor cell growth and proliferation." (PMID 38576021, 2024). "Moreover, this cluster tumor is associated with amplified TERC, TERT, MYC, CCND1, and BCL2L1." (PMID 34815793, 2021). "This shift in prooxidant enzyme and antioxidant enzyme balance may cause the imbalance of proapoptotic (BAX and BAD) and antiapoptotic genes (BCL2 and BCL2L1), resulting in a tumor microenvironment which is in favor of surviving and resistant to apoptosis in Tg tumor." (PMID 33456675, 2020). "Therefore, repression of MYC and BCL2L1 might contribute to the tumor suppressor effects of FOXO1 in PMBL." (PMID 24977668, 2014). "Compared to other Bcl2 family members, we found relatively high average mRNA levels of Bcl‐xl (BCL2L1), Bax, and Mcl‐1 in the three tumor organoid lines, while another key member Bcl‐2 exhibited comparatively lower expression." (PMID 40405831, 2025). "Conversely, when BCL2L1 was knocked down in the SW1783 cell line, tumor growth was significantly inhibited compared to the CLU-OE group." (PMID 40606578, 2025).